MIR4768 (microRNA 4768)
Synonyms: hsa-mir-4768
Gene: MicroRNA gene on chromosome X (17,425,881 to 17,425,954, forward strand). Ensembl gene ENSG00000265465.
Homologues: Orthologues: chimpanzee MIR4768 (100% identical).